CARTPT (CART prepropeptide)
Description:
Satiety factor closely associated with the actions of leptin and neuropeptide Y; this anorectic peptide inhibits both normal and starvation-induced feeding and completely blocks the feeding response induced by neuropeptide Y and regulated by leptin in the hypothalamus. It promotes neuronal development and survival in vitro.
Synonyms: CART
Tractability: Antibody: UniProt places it where antibodies can reach, with high confidence; UniProt predicts a signal peptide or a membrane-spanning region; its Gene Ontology location is reachable by antibodies, with medium confidence.
Gene: Protein-coding gene on chromosome 5 (71,719,275 to 71,721,048, forward strand). Ensembl gene ENSG00000164326.
Subcellular location: Secreted
Gene Ontology:
Molecular function: protein binding; neuropeptide hormone activity
Biological process: intracellular glucose homeostasis; negative regulation of bone resorption; positive regulation of blood pressure; positive regulation of epinephrine secretion; positive regulation of transmission of nerve impulse; adult feeding behavior; cell-cell signaling; cellular response to starvation; circadian regulation of gene expression; G protein-coupled receptor signaling pathway; negative regulation of appetite; negative regulation of osteoclast differentiation; positive regulation of MAPK cascade; signal transduction; behavioral response to cocaine; cAMP biosynthetic process; cellular response to estradiol stimulus; circadian rhythm; conditioned place preference; detection of chemical stimulus involved in sensory perception of pain; detection of temperature stimulus involved in sensory perception of pain; drinking behavior; glucose metabolic process; intracellular calcium ion homeostasis; negative regulation of cytosolic calcium ion concentration; and 32 more
Cellular component: extracellular region; secretory granule; cytoplasm; neuronal cell body
Genetic constraint (gnomAD): Loss-of-function variants: 6 observed, 12.38 expected, observed/expected ratio (o/e) 0.48, 90% interval 0.26 to 0.96. The upper end of that interval is the gene's LOEUF score, 0.96, which puts it in group 4 of 6, group 1 being the genes least tolerant of losing a copy. Missense variants: 135 observed, 149.73 expected, observed/expected ratio (o/e) 0.9, 90% interval 0.78 to 1.04. Synonymous variants: 75 observed, 69.11 expected, observed/expected ratio (o/e) 1.09, 90% interval 0.9 to 1.32.
Homologues: Orthologues: chimpanzee CARTPT (99% identical), mouse Cartpt (97% identical), rat Cartpt (95% identical), guinea pig CARTPT (94% identical), pig CARTPT (94% identical), dog CARTPT (89% identical), macaque CARTPT (74% identical), tropical clawed frog cartpt (68% identical), zebrafish cart2 (56% identical), zebrafish cart1 (51% identical), zebrafish CARTPT (49% identical), zebrafish cart3 (49% identical).
Diseases named in the same sentence as CARTPT in open-access papers:
CARTPT is named in the same sentence as 81 diseases in open-access papers, as found by Europe PMC text mining. Sharing a sentence is not in itself a finding about the gene and the disease. The quoted sentences say what the papers report.
Obesity (40 papers, 2005 to 2025). Accumulation of substantial excess body fat. "CARTPT encodes a neuropeptide involved in regulating appetite and satiety, with potential implications for connecting obesity and AD." (PMID 38478169, 2024). "Cocaine- and amphetamine-regulated transcript prepropeptide gene (CARTPT), which maps to the chromosome 5q13-14 and expresses the cocaine- and amphetamine-regulated transcript (CART) protein, has been recognized to be a susceptibility locus for obesity." (PMID 37521830, 2022). "Considering the role of genetic factors in the incidence of many diseases, the CARTPT rs2239670 variant was found to be associated with MetS presence among adults with obesity in present study." (PMID 36404325, 2022). "In this regard, leu34Phe missense mutation in CARTPT gene was detected in Italian subjects with early-onset obesity." (PMID 37521830, 2022). "So, our aim was to investigate the mediating role of glycemic indices in the relationship between CARTPT rs2239670 polymorphism, socio-demographic and psychological factors and metabolic risk factors and the presence of MetS in adults with obesity." (PMID 36404325, 2022). "There is accumulating evidence showing that polymorphisms in the CARTPT gene are associated with obesity." (PMID 36404325, 2022). "Epidemiologic studies show that cocaine- and amphetamine-regulated transcript prepropeptide (CARTPT) gene polymorphism modifies diet-obesity relationships." (PMID 31918705, 2020). "CARTPT can encode a neuropeptide involved in the regulation of appetite and satiety and may play a role in the association of obesity with AD." (PMID 39027505, 2024). "Similarly, heterozygous CARTPT mutations have been described in a family with severe obesity and reduced metabolic rates." (PMID 38019584, 2024). "Previous evidence has revealed that polymorphisms in the CARTPT gene are linked to human obesity." (PMID 37521830, 2022). "Likewise, several prior studies have identified polymorphisms in the CART gene of individuals with obesity and it seems that any alterations in CARTPT are associated with reduced metabolic rate, hyperphagia, obesity and increased the risk of type II diabetes." (PMID 36404325, 2022). "Various bioinformatics studies suggest that midlife obesity is a risk factor for AD, CARTPT may be central in linking these two disease conditions." (PMID 35958988, 2022). "The present study attempted to clarify the effects of dietary factors as a modulator, which can modify the association of CARTPT gene polymorphism and cardio-metabolic risk factors, therefore, it can affects the genetic susceptibility to a variety of chronic diseases such as obesity." (PMID 34876220, 2021). "It has been identified that CART prepropeptide gene polymorphism is associated with obesity." (PMID 31918705, 2020). "However, the specific environmental factors particularly diet that interact with obesity-predisposing gene variants may contribute to these inconsistencies and modulate the effects of CARTPT gene polymorphisms on obesity and its-related diseases." (PMID 36404325, 2022). "Since the rs2239670 variant located in the intron 1 of CARTPT gene and its strong effects on obesity and related metabolic factors may be removed during splicing process of mRNA encoding CART proteins, effects of this variant on CART function are still unknown." (PMID 37521830, 2022). "Also as a metabolic disorder, middle-aged obesity may increase the risk of AD, and CARTPT was now identified as a target for antiobesity drugs, having a high value in connecting obesity and AD." (PMID 35996379, 2022). "The cocaine- and amphetamine-regulated transcript prepropeptide gene (CARTPT) maps to human chromosome 5q13–14, is a positional candidate for obesity." (PMID 36404325, 2022). "The present study indicated that the relationships between CARTPT rs2239670 and obesity and its-related metabolic parameters depend on adherence to the dietary NEAC." (PMID 37521830, 2022).
Obesity (continued). "The association between cocaine- and amphetamine-regulated transcript prepropeptide gene (CARTPT) and obesity-related outcomes has shown in the epidemiological studies." (PMID 37521830, 2022). "It should be taken into account that all variants in CARTPT gene have not been related to obesity phenotypes and findings in this regard are conflicting." (PMID 37521830, 2022). "For example, in accordance with the results of Walder study, C1442G polymorphism of CARTPT gene was not related to obesity among Pima Indians." (PMID 37521830, 2022). "The latest scientific studies have indicated that variations in the CARTPT gene might influence obesity, metabolic syndromes (MetS) and its components." (PMID 37521830, 2022). "To date, there is no study regarding the interaction between the CARTPT polymorphisms and dietary indices in relation to cardio-metabolic traits and hypothalamic hormones in obesity and this is the main strength of current study." (PMID 31918705, 2020). "Our findings revealed the interactive role of DQI-I in reducing obesity related metabolic profile including BMI, FM and FSG and AgRP in AA genotype of CARTPT; no human study is available evaluating the relationship between AgRP and CART gene polymorphisms." (PMID 31918705, 2020). "Indeed, resistance to anorexigenic signaling pathways are well-characterized in obesity (e.g., leptin and insulin), including neuropeptides such as CARTPT." (PMID 29746501, 2018). "Thus, the results of modification effect of diet on the associations of CARTPT with obesity and metabolic factors were not homogenous." (PMID 37521830, 2022). "Our findings revealed an association between the rs2239670 SNP of the CARTPT gene and obesity and exhibited evidences several interactions between this variant and dietary indices in terms of BMR, WC, FM, serum glucose and AgRP particularly in terms of CARTPT–DQI-I associations." (PMID 31918705, 2020).
Anxiety (17 papers, 2008 to 2024). Intense feelings of nervousness, tension, or panic often arise in response to interpersonal stresses. "Studies of genetic polymorphisms in psychiatric disorders have shown that CARTPT gene mutation exhibits increased anxiety and depression." (PMID 35806070, 2022).
depression (13 papers, 2008 to 2024). "In downregulated DEGs, CARTPT is a key marker for depression." (PMID 35958988, 2022).
Hypertension (8 papers, 2016 to 2023). The presence of chronic increased pressure in the systemic arterial system. "In the current study, we aimed to evaluate the interaction of CARTPT gene polymorphism with diet quality indices including dietary approaches to stop hypertension (DASH) and Mediterranean diet score (MDS) on cardio-metabolic risk factors." (PMID 34876220, 2021). "Moreover, the studies have shown that genetic polymorphisms in the CARTPT gene might affect susceptibility to MetS and its components such as dyslipidemia, high blood pressure and hyperglycemia." (PMID 37521830, 2022).
breast carcinoma (6 papers, 2020 to 2025). "CARTPT, known for its role in cocaine- and amphetamine-regulated transcript signaling, has been implicated in breast cancer cell survival and tamoxifen resistance, underscoring its relevance in therapeutic response and tumor behavior." (PMID 40870889, 2025). "Assessment of link between 10 energy homeostasis genes (including CARTPT) and breast cancer risk in connection with ethnical ancestry, body size measurements and menopausal status." (PMID 37373130, 2023). "We then showed that cocaine and amphetamine regulated transcript prepropeptide (CARTPT) and breast cancer-associated transcript 54 (BRCAT54) mRNA—previously shown by microarray analysis to be highly expressed in DCIS—were detectable in these samples." (PMID 35144664, 2022). "Furthermore, we explored whether the RNA contained cocaine- and amphetamine-regulated transcript prepropeptide (CARTPT) and breast cancer-associated transcript 54 (BRCAT54) mRNAs, which a previous microarray study found to be highly expressed in DCIS." (PMID 35144664, 2022). "In addition, five SNPs in three genes (ADIPOQ rs182052, rs822391 and rs7649121, CARTPT rs3846659, and LEPR rs12059300) had an effect modification on the association between IGFBP-3 serum concentration and breast cancer risk (Pinteraction < 0.05, adjusted Pinteraction < 0.20)." (PMID 35115550, 2022). "Among the key genes found in these enriched categories, TPSD1, FABP4, CARTPT, TRH, CSN3, and MMP9 stand out based on previously published data, which suggest their critical roles in cancer progression, including breast cancer." (PMID 40870889, 2025).
Insulin resistance (4 papers, 2021 to 2026). Increased resistance towards insulin, that is, diminished effectiveness of insulin in reducing blood glucose levels. "In other words, dietary NEAC could not modulate detrimental effects of CARTPT rs2239670 polymorphism on insulin resistance indices (HOMA and QUICKI) in participants carrying AA genotype." (PMID 37521830, 2022).
alcoholism (2 papers, 2016 to 2022). "A positive association between CARTPT rs2239670 variant and alcoholism has been reported in the Korean population." (PMID 37521830, 2022). "Other studies which have specifically investigated the association of the CARTPT rs2239670 polymorphism with addictive behaviors such as alcohol dependence have confirmed a positive relation." (PMID 37521830, 2022).
Alzheimer disease (1 paper, 2022). A progressive, neurodegenerative disease characterized by loss of function and death of nerve cells in several areas of the brain leading to loss of cognitive function such as memory and language. "Using the “rms” package (version 6.2-0) in R (version 4.0.2), a nomogram model based on the 3 specific genes (CARTPT, EPHA5, and SERPINA3) was constructed to predict the risk of Alzheimer's disease (GSE122063)." (PMID 35996379, 2022).
atherosclerosis (1 paper, 2022). A disease characterized by the build-up of fatty material and calcium deposition in the arterial wall resulting in partial or complete occlusion of the arterial lumen. "Nevertheless, the role of CARTPT and PDZRN3 methylation in atherosclerosis has been firstly revealed in our study." (PMID 35915606, 2022). "In GSE20129 dataset, CARTPT, RYR2, CNTN4, PDZRN3, and SLC22A3 all showed differential expression levels in atherosclerosis vs. nonatherosclerotic samples." (PMID 35915606, 2022).
carcinoids (1 paper, 2022). "Interestingly, some of the peptidergic genes expressed in only minor subpopulations of normal PNECs (e.g. NPW, NPPA, SST, CARTPT) were detected in many carcinoids, whereas the nearly ubiquitous PNEC peptidergic gene CALCA was absent from most carcinoids." (PMID 36469459, 2022).
tumor (22 papers, 2018 to 2025). "It is worth noting that many genes were dramatically upregulated specifically in ACTH+&CRH + pheochromocyte when compared with the other tumor cell types, such as GAL, POMC, PNMT, and CARTPT." (PMID 34905486, 2021). "Some peptidergic genes such as CALCA and GRP that are expressed in almost all normal PNECs were expressed in few if any tumor cells, whereas NPW, NMB, and CARTPT that are expressed in only rare PNECs were expressed in most (NPW) or many (NMB, CARTPT) of the tumor cells." (PMID 36469459, 2022).
cancer (9 papers, 2018 to 2025). A tumor composed of atypical neoplastic, often pleomorphic cells that invade other tissues. "In various cancer cell lines, CARTPT acts as an oncogene, promoting cellular survival through the activation of the ERK pathway, stimulation of pro-survival molecules, inhibition of apoptosis, and an increase in cyclin D1 levels." (PMID 40870889, 2025). "In various cancer cell lines, CARTPT acts an oncogene, enhancing cellular survival by the activation of the ERK pathway, the stimulation of other pro-survival molecules, the inhibition of apoptosis or the increase in cyclin D1 levels." (PMID 37373130, 2023).
CARTPT also shares sentences with these, for which no sentence is quoted: Anorexia (14 papers); diabetes (6); Infertility (4); psychiatric disorder (4); Hyperglycemia (3); ischemia (3); neurodegenerative disease (3); Parkinson disease (3); Stroke (3); type II diabetes (3); adenocarcinoma (2); alcohol abuse (2); Cachexia (2); Cerebral ischemia (2); endotoxemia (2); glioma (2); Hirschsprung disease (2); Huntington disease (2); ischemic stroke (2); memory impairment (2); metabolic syndrome (2); mood disorder (2); morbid obesity (2); neuroendocrine tumors (2); osteoporosis (2); Tremor (2); ulcerative colitis (2); vitamin D deficiency (2); amnesia (1); ANCA-associated vasculitis (1).
A further 39 diseases each share a sentence with CARTPT in 1 paper.